GTF2B (general transcription factor IIB)
Description:
General transcription factor that plays a role in transcription initiation by RNA polymerase II (Pol II). Involved in the pre-initiation complex (PIC) formation and Pol II recruitment at promoter DNA. Together with the TATA box-bound TBP forms the core initiation complex and provides a bridge between TBP and the Pol II-TFIIF complex. Released from the PIC early following the onset of transcription during the initiation and elongation transition and reassociates with TBP during the next transcription cycle. Associates with chromatin to core promoter-specific regions. Binds to two distinct DNA core promoter consensus sequence elements in a TBP-independent manner; these IIB-recognition elements (BREs) are localized immediately upstream (BREu), 5'-[GC][GC][GA]CGCC-3', and downstream (BREd), 5'-[GA]T[TGA][TG][GT][TG][TG]-3', of the TATA box element. Modulates transcription start site selection. Also exhibits autoacetyltransferase activity that contributes to the activated transcription.
Synonyms: TF2B; TFIIB
Tractability: Small molecule: a structure with a bound ligand is known. PROTAC: ubiquitination databases record sites on it; its protein half-life has been measured.
Gene: Protein-coding gene on chromosome 1 (88,852,633 to 88,891,944, reverse strand). Ensembl gene ENSG00000137947.
Subcellular location: Nucleus; Chromosome
Subcellular location (Human Protein Atlas): Nuclear bodies; Nucleoplasm
Pathways (Reactome):
Gene expression (Transcription): RNA Polymerase II Pre-transcription Events; RNA Polymerase II Promoter Escape; RNA Polymerase II Transcription Initiation; RNA Polymerase II Transcription Initiation And Promoter Clearance; RNA Polymerase II Transcription Pre-Initiation And Promoter Opening; RNA polymerase II transcribes snRNA genes
Disease: HIV Transcription Initiation; RNA Polymerase II HIV Promoter Escape; Transcription of the HIV genome
Gene Ontology:
Molecular function: DNA-binding transcription factor binding; nuclear thyroid hormone receptor binding; promoter-specific chromatin binding; protein binding; protein-lysine-acetyltransferase activity; RNA polymerase II complex binding; RNA polymerase II core promoter sequence-specific DNA binding; RNA polymerase II general transcription initiation factor activity; TBP-class protein binding; zinc ion binding; acetyltransferase activity; DNA binding
Biological process: positive regulation of core promoter binding; protein acetylation; RNA polymerase II core complex assembly; RNA polymerase II preinitiation complex assembly; transcription by RNA polymerase II; transcription initiation at RNA polymerase II promoter; transcriptional start site selection at RNA polymerase II promoter; viral transcription; DNA-templated transcription initiation; chromosome organization; gene expression; meiotic sister chromatid cohesion; spindle assembly; transcription preinitiation complex assembly
Cellular component: chromosome; nuclear body; nucleoplasm; nucleus; protein-DNA complex; RNA polymerase II transcription regulator complex; transcription factor TFIID complex; transcription preinitiation complex; cell division site; condensed chromosome; germinal vesicle; kinetochore
Genetic constraint (gnomAD): Loss-of-function variants: 13 observed, 23.62 expected, observed/expected ratio (o/e) 0.55, 90% interval 0.36 to 0.88. The upper end of that interval is the gene's LOEUF score, 0.88, which puts it in group 3 of 6, group 1 being the genes least tolerant of losing a copy. Missense variants: 156 observed, 265.73 expected, observed/expected ratio (o/e) 0.59, 90% interval 0.51 to 0.67. Synonymous variants: 87 observed, 86.69 expected, observed/expected ratio (o/e) 1, 90% interval 0.84 to 1.2.
Homologues: Orthologues: dog GTF2B (100% identical), pig GTF2B (100% identical), mouse Gtf2b (99% identical), rat Gtf2b (99% identical), macaque GTF2B (98% identical), chimpanzee GTF2B (98% identical), guinea pig GTF2B (95% identical), tropical clawed frog gtf2b (94% identical), zebrafish gtf2b (94% identical), Drosophila melanogaster TfIIB (79% identical), Caenorhabditis elegans ttb-1 (59% identical). Paralogues in human: BRF2 (21% identical), BRF1 (19% identical).
Diseases named in the same sentence as GTF2B in open-access papers:
GTF2B is named in the same sentence as 23 diseases in open-access papers, as found by Europe PMC text mining. Sharing a sentence is not in itself a finding about the gene and the disease. The quoted sentences say what the papers report.
Alzheimer disease (1 paper, 2023). A progressive, neurodegenerative disease characterized by loss of function and death of nerve cells in several areas of the brain leading to loss of cognitive function such as memory and language. "Moreover, GTF2B was proposed as a potential cohub gene in Alzheimer’s disease and DM." (PMID 37372101, 2023).
colorectal cancer (1 paper, 2023). A primary or metastatic malignant neoplasm that affects the colon or rectum. "GTF2B has been identified as a prognostic marker for colorectal cancer and neuroblastoma, while GTF2H1 is a p62 subunit of complex transcription factor IIH (TFIIH) that regulates nucleotide excision repair and transcription." (PMID 37260986, 2023).
heart failure (1 paper, 2021). Inability of the heart to pump blood at an adequate rate to meet tissue metabolic requirements. "We proposed that under the regulation of Nkx2-5 and Gtf2b, activation of components of muscle and mitochondrial dysfunction were induced in cardiomyocytes with high Nppa expression, resulting in heart failure by a trans-omics approach." (PMID 33854108, 2021).
pituitary adenomas (1 paper, 2024). "There was a positive correlation between GTF2B and AIP mRNA expression, with high-grade GH-secreting pituitary adenomas having both lower GTF2B and AIP expression." (PMID 38479600, 2024).
preeclampsia (1 paper, 2023). Preeclampsia is a hypertensive disorder of pregnancy that is characterized by new-onset hypertension with proteinuria presenting after 20 weeks of gestation, and depending on mild or severe forms may initially present with severe headache, visual disturbances, and hyperreflexia. "For the first time, the transcriptional factors CEBPB and GTF2B were described, and their involvement in EVTs dysfunction in preeclampsia was reported." (PMID 36981026, 2023). "After further in vitro cell experiments, it was found that CEBPB and GTF2B can regulate cell apoptosis and invasion, which may be involved in the preeclampsia pathological processes." (PMID 36981026, 2023).
squamous cell cervical cancer (1 paper, 2002). "It was found that the level of expression of both clone G30CI (human guanine nucleotide binding protein β5) and clone G32C2B (human general transcription factor IIB) were greatly upregulated in stage 1B squamous cell cervical cancer." (PMID 11870519, 2002).
cancer (11 papers, 2009 to 2024). A tumor composed of atypical neoplastic, often pleomorphic cells that invade other tissues. "In CRC, LINC00355 promotes ITGA2 expression by recruiting GTF2B, a critical transcription factor involved in regulating various cancers, thereby promoting cancer progression." (PMID 38125763, 2023). "RNU2-2P is a pseudogene that is involved in cancer and is inhibited by TBP, TAF5 and GTF2B." (PMID 38674117, 2024).
infection (5 papers, 2012 to 2021). The state of being infected such as from the introduction of a foreign agent such as serum, vaccine, antigenic substance or organism. "WT MHV68 infection reduced the levels of Pol II subunits Polr2a (Rpb1), Polr2b (Rpb2) and Gtf2B (TFIIB) beginning at 20 hpi." (PMID 32032393, 2020).
tumor (5 papers, 2019 to 2023). "Lastly, five genes including GSKIP, SELENOF, RAP1B, UBE2D3, and GTF2B, were found to be co-expressed in both adjacent healthy tissue and tumor tissue." (PMID 37365287, 2023). "CD8 dependence of neoepitope-elicited tumor immunity was tested in the case of the peptide TGAARFDEF (derived from Gtf2b) by depletion of neoepitope-immunized mice by anti-CD8 depleting antibody or an isotype control antibody during the priming phase alone, as described in the Methods." (PMID 31219806, 2019). "Transcription factor general transcription factor IIB (GTF2B) could regulate aryl hydrocarbon receptor-interacting protein (AIP) protein expression and influence tumor phenotypes in growth hormone-secreting PA." (PMID 38023219, 2023).
GTF2B also shares sentences with these, for which no sentence is quoted: breast carcinoma (4 papers); ovarian carcinoma (2); viral infection (2); adenocarcinoma (1); breast tumors (1); cardiac hypertrophy (1); colon cancers (1); dyslipidemia (1); gastric carcinoma (1); hepatoma (1); insulinoma (1); leukemia (1); neuroblastoma (1); ZIKV infection (1).